CFTR (CF transmembrane conductance regulator)
Diseases named in the same sentence as CFTR in open-access papers (continued):
Sharing a sentence is not in itself a finding about the gene and the disease.
cystic fibrosis (continued). "Cystic Fibrosis is a common monogenic disease caused by mutations in the Cystic Fibrosis Transmembrane conductance Regulator (CFTR) gene coding for an ATP-dependent anion channel-protein required to regulate sweat, digestive juices and mucus components." (PMID 22028919, 2011). "Mutations of the CFTR gene in humans affect functioning of the chloride ion channels in cell membranes, leading to cystic fibrosis." (PMID 22030022, 2011). "The cystic fibrosis ΔF508 mutation that resides in the NBD1 domain of CFTR directly affects stability of this domain in vitro." (PMID 21152102, 2010). "Cystic fibrosis is a common inherited genetic disorder, caused by a mutation in the gene encoding the cystic fibrosis transmembrane conductance regulator (CFTR) protein which is expressed in many different cells." (PMID 20374629, 2010). "Cystic fibrosis is a chronic autosomic recessive syndrome, caused by mutations in the CF Transmembrane Conductance Regulator (CFTR) gene, a chloride channel expressed on the apical side of the airway epithelial cells." (PMID 21994643, 2010). "We identified such a mechanism as the origin of the mild to asymptomatic phenotype observed in cystic fibrosis patients homozygous for the E831X mutation (2623G>T) in the CFTR gene." (PMID 20949073, 2010). "More than 1,500 mutations found in the gene encoding CFTR lead to cystic fibrosis, the most common lethal genetic disease amongst Caucasians." (PMID 21152102, 2010). "Cystic fibrosis is widely regarded solely as a defect in ion transport arising from a heritable mutation in the cystic fibrosis transmembrane conductance regulator (CFTR)." (PMID 20644644, 2010). "Cystic fibrosis is caused by a mutation in the CFTR-gene leading to dysfunction of the exocrine glands." (PMID 20105324, 2010). "Cystic fibrosis is caused by mutations in the CFTR gene that impair the function of CFTR, a cAMP-regulated anion channel." (PMID 20843337, 2010). "Cystic fibrosis is caused by mutations in the CFTR gene, which encodes a chloride ion channel active primarily in the apical membrane of secretory epithelia." (PMID 21097980, 2010). "For example, patients with cystic fibrosis, a genetic disease caused by CFTR mutations, frequently present with chronic lung infection but the exact cause remains obscure." (PMID 21151921, 2010). "An example of a disease whose incidence is influenced primarily by genetic factors is cystic fibrosis, an autosomal recessive disease from a mutation in the cystic fibrosis transmembrane conductance regulator (CFTR)." (PMID 19208189, 2009). "Cystic fibrosis is one of the most common fatal autosomal recessive disorders in the Caucasian population caused by mutations of gene for the cystic fibrosis transmembrane conductance regulator (CFTR)." (PMID 19277125, 2009). "Cystic fibrosis is an autosomal recessive disorder caused by mutations of the CF transmembrane conductance regulator (CFTR), which acts as a chloride channel and also participates in the regulation of other ions and proteins." (PMID 19649303, 2009). "In cystic fibrosis, the most frequent mutant variant of the cystic fibrosis transmembrane conductance regulator (CFTR), F508del-CFTR protein, is misfolded and retained in the endoplasmic reticulum (ER)." (PMID 20041182, 2009). "Deletion of Tyr490 is known to induce defective or no expression of P-gp and the deletion of the equivalent residue of Tyr490 in CFTR, Phe508, is the major cystic fibrosis causing mutation." (PMID 19159494, 2009). "Cystic fibrosis is caused by defects in the gene encoding the cystic fibrosis transmembrane conductance regulator (CFTR)." (PMID 19649303, 2009). "Dysfunctional CFTR in the airways is associated with elevated levels of NFκB mediated IL-8 signaling leading to neutrophil chemotaxis and chronic lung inflammation in cystic fibrosis." (PMID 19247502, 2009).
cystic fibrosis (continued). "Sodium butyrate has also been reported to enhance splicing activity in CFTR, to correct reading frame of a point mutation associated with cystic fibrosis, and restore chloride channel function." (PMID 20020055, 2009). "Cystic fibrosis is an autosomal recessive disorder due to mutations in the Cystic Fibrosis Transmembrane conductance Regulator (CFTR) gene that is located on chromosome 7 in human." (PMID 18682840, 2008). "Cystic Fibrosis is an autosomal recessive genetic disorder caused by a genetic defect in the cystic fibrosis transmembrane conductance regulator (CFTR), a protein that functions primarily as a chloride channel." (PMID 18846238, 2008). "Extended Cystic Fibrosis Transmembrane Receptor (CFTR) mutation analysis showed that the patient was positive for the L997F mutation in addition to the ΔF508, both known cystic fibrosis-causing mutations." (PMID 18501000, 2008). "Recently, the role of the epithelial sodium channel ENaC has been pointed out in the pathophysiology of cystic fibrosis, a disease due to mutations in the CFTR gene and causing bronchiectasis in the airways." (PMID 18507830, 2008). "Cystic fibrosis is an autosomal recessive disorder that is caused by mutations in the CF transmembrane conductance regulator (CFTR) gene." (PMID 18047640, 2007). "One of the main findings in all investigations is the detection of mostly rare CFTR mutations showing a different spectrum of detected mutations than in cystic fibrosis and congenital bilateral aplasia of the vas deferens (CBAVD)." (PMID 17204147, 2007). "Cystic fibrosis is caused by mutations in the gene encoding the cystic fibrosis transmembrane conductance regulator (CFTR) protein, which acts as a chloride channel activated by cyclic AMP (cAMP)." (PMID 17394637, 2007). "The mutated gene product of ABCC7 (CFTR) is involved in the pathogenesis cystic fibrosis, and some other mutated ABC transporter genes contribute to a number of hereditary diseases and disorders." (PMID 17726528, 2007). "It is reported that mutations at the cystic fibrosis transmembrane conductance regulator gene (CFTR) cause cystic fibrosis, the most prevalent severe genetic disorder in individuals of European descent." (PMID 18096053, 2007). "Cystic fibrosis is an autosomal recessive disease caused by mutations in the Cystic Fibrosis Transmembrane conductance Regulator (CFTR) gene." (PMID 16571124, 2006). "Cystic fibrosis is a common inherited disease caused by mutations in the gene encoding the cystic fibrosis transmembrane conductance regulator (CFTR), which is an epithelial chloride channel." (PMID 16875506, 2006). "Cystic fibrosis is caused by mutations in the gene encoding for the CF transmembrane conductance regulator (CFTR) protein, which acts as a chloride channel after activation by cyclic AMP (cAMP)." (PMID 17018149, 2006). "In vitro studies have investigated the effects of CFTR dysfunction in cystic fibrosis [CFTR mutation] patients on cytokine secretion in white blood cell and respiratory epithelial cell populations." (PMID 16571116, 2006). "Although cystic fibrosis is caused by mutations in the cystic fibrosis transmembrane conductance regulator (CFTR) gene, the severity of disease is highly variable indicating the influence of modifier genes." (PMID 15921521, 2005). "Mutations in the CFTR gene can cause cystic fibrosis and are associated with abnormal Cl- and Na+ ion transport in several tissues including the lungs, pancreas, gastrointestinal tract, liver, sweat glands and male reproductive organs." (PMID 15967026, 2005). "Cystic fibrosis is caused by mutations in the cystic fibrosis transmembrane regulator (CFTR) gene and early alterations are primarily found in the small airways." (PMID 16274485, 2005). "Mutations in the cystic fibrosis transmembrane conductance regulator (CFTR) gene can cause cystic fibrosis, and mutations in ABCA1 and ABCA3 are responsible for respectively Tangier disease and fatal surfactant deficiency." (PMID 15967026, 2005).
cystic fibrosis (continued). "The ABC transporter most widely investigated is the cystic fibrosis transmembrane conductance regulator (CFTR), because mutations in this gene are responsible for the development of cystic fibrosis." (PMID 15967026, 2005). "Mutations affecting CFTR channel function or membrane expression can produce a wide range of clinical manifestations, from asymptomatic carriers to individuals with full-blown cystic fibrosis." (PMID 41510163, 2026). "We sought to determine whether a cystic fibrosis transmembrane conductance regulator (CFTR) mRNA could be administered to the fetus via the transamniotic route as a potential strategy for the perinatal management of cystic fibrosis-associated meconium ileus." (PMID 41959539, 2026). "In addition, the prevalence of pathogenic CFTR GVs in the colorectal cancer population was significantly higher than expected suggesting an increased cancer risk not only in cystic fibrosis patients, but also in heterozygous CFTR GV carriers." (PMID 41546701, 2026). "Cystic fibrosis is a genetic disorder characterized by progressive lung disease and exocrine pancreatic insufficiency caused by variants in the cystic fibrosis transmembrane conductance regulator (CFTR) gene." (PMID 41545622, 2026). "We also detected one case each (2.5% of total abnormalities) of Wilson’s disease (mutations in ATP7B), cystic fibrosis (mutations in CFTR), Cockayne syndrome (mutations in ERCC6), auditory neuropathy (mutations in OTOF), and autosomal recessive polycystic kidney disease (mutations in PKHD1)." (PMID 41329681, 2025). "Cystic fibrosis is an autosomal recessive genetic disorder caused by variants in the cystic fibrosis transmembrane conductance regulator (CFTR) gene, which encodes an epithelial ion channel responsible for chloride and bicarbonate transport across cell membranes." (PMID 41465880, 2025). "For example, therapies targeting the cystic fibrosis transmembrane conductance regulator (CFTR) modulation for cystic fibrosis, a genetic mutation disease, may offer valuable insights." (PMID 40462219, 2025). "Furthermore, SORT-LNPs encoding Cas9 mRNA were able to correct cystic fibrosis CFTR driver mutations in patient derived cells, organoid models, and mouse models." (PMID 41542091, 2025). "Donor #4 was a woman with a diagnosis of cystic fibrosis (homozygous F508del mutation in the CFTR)." (PMID 39859153, 2025). "Cystic fibrosis is a severe geneticdisorder arising frommutations in the CFTR gene, which encodes the Cystic Fibrosis TransmembraneConductance Regulator (CFTR) protein.−, CFTR functions as anion channel, facilitating chloride ion transport across epithelialcell membranes." (PMID 41358137, 2025). "Cystic fibrosis is an autosomal recessive disorder caused by variants in the gene encoding cystic fibrosis transmembrane conductance regulator (CFTR), leading to multisystem involvement, particularly in the lungs, gastrointestinal system, pancreas, and biliary tract." (PMID 41070102, 2025). "To date, more than 2100 variants in the CFTR gene have been described; however, approximately 719 have been shown to cause cystic fibrosis, as they lead to a significant decrease in or complete absence of CFTR protein function, a condition essential for the clinical manifestation of the disease." (PMID 40868633, 2025). "However, it appears that the degree of residual CFTR protein function can also affect, either directly or indirectly, the pathogenesis and progression of cystic fibrosis–associated bone disease." (PMID 41300552, 2025). "For example, cystic fibrosis treatments could transport genes encoding the functional CFTR protein, thereby correcting genetic defects that lead to mucus buildup in the lungs." (PMID 40149668, 2025).
cystic fibrosis (continued). "As a target, the authors chose ΔF508-CFTR.This frameshiftmutation in CFTR, is the most common mutation leading to the cysticfibrosis phenotype, causing protein destabilization, and proteasomaldegradation before trafficking of the channel from the ER to the cellsurface." (PMID 39692621, 2025). "Cystic fibrosis is an autosomal recessive genetic disorder caused by various mutations in the cystic fibrosis transmembrane conductance regulator (CFTR) gene, which results in reduced chloride and bicarbonate ions secretion and increased sodium ions absorption." (PMID 40406132, 2025). "Large cohort analyses have shown that mutations in the CFTR gene, commonly associated with cystic fibrosis, are present in approximately 6-8% of patients with idiopathic pancreatitis, implicating impaired ductal function and increased susceptibility to pancreatic injury." (PMID 40432658, 2025). "Cystic fibrosis, a severe genetic disorder stemming from mutations in the Cystic Fibrosis Transmembrane Conductance Regulator (CFTR) gene, is characterized by a complex interplay of chronic inflammation and heightened oxidative stress, resulting in substantial patient morbidity." (PMID 40573184, 2025). "Another study on mice has also indicated that the F508del-CFTR mutation may play a role in bone disease by impairing the rate of new bone formation in infants and young children with cystic fibrosis." (PMID 41300552, 2025). "In Cystic fibrosis that technique constitutes a widely employed ex vivo tool for research, facilitating the functional assessment of the transmembrane conductance regulator (CFTR) protein, whose dysfunction underlies the pathophysiology of the disease." (PMID 40943780, 2025). "Cao H., Ouyang H., Laselva O., Bartlett C., Zhou Z.P., Duan C., GunawardenaT., Avolio J., Bear C.E., Gonska T., Hu J., Moraes T.J.A helper-dependent adenoviral vector rescues CFTR to wildtypefunctional levels in cystic fibrosis epithelial cells harbouringclass I mutations." (PMID 40297296, 2025). "More than 2000 cystic fibrosis-related mutations have been detected in the CFTR gene." (PMID 40276426, 2025). "The sweat test can confirm the diagnosis and may be associated with the search for genetic mutations related to cystic fibrosis and CFTR protein function tests." (PMID 40398368, 2025). "Cystic fibrosis is a life-shortening autosomal recessive disorder caused by mutations in the CFTR (cystic fibrosis transmembrane conductance regulator) gene, which encodes a cAMP-regulated chloride and bicarbonate channel located on the apical surface of epithelial cells." (PMID 41516108, 2025). "Cystic fibrosis is an autosomal recessive disorder caused by variants in the CFTR gene." (PMID 41496868, 2025). "Likewise, numerous clones of P. aeruginosa can survive in macrophages that are deficient in the cystic fibrosis-causing gene CFTR." (PMID 40901975, 2025). "The purpose of this report is to describe an infantile phenotype with significant complications of a patient with cystic fibrosis linked to the rare c.1375_1383del variant and highlight challenges in managing rare CFTR variants in high-consanguinity regions like Saudi Arabia." (PMID 40933696, 2025). "CFTR, linked to cystic fibrosis, causes metabolic irregularities that impact pain." (PMID 40313396, 2025). "Cystic fibrosis is a common autosomal recessive disease caused by mutations of the gene encoding a chloride/bicarbonate channel known as the CF transmembrane conductance regulator (CFTR)." (PMID 40131363, 2025). "One well-known example is the common F508del mutation in CFTR, leading to cystic fibrosis." (PMID 39674817, 2025). "Owing to the absence of a seminal vesicle, a possible diagnosis of cystic fibrosis was considered; however, PCR amplification of a blood sample followed by sequence-based analysis was performed to screen for mutations in the CFTR gene responsible for cystic fibrosis." (PMID 40937234, 2025).
cystic fibrosis (continued). "In two 52-week, randomized, double-blind, active-controlled trials (Trial 1, NCT05033080; Trial 2, NCT05076149), the efficacy of ALYFTREK and Trikafta was evaluated in 971 patients aged 12 years and older with cystic fibrosis who had at least one F508del mutation or an adaptive CFTR gene mutation." (PMID 40430547, 2025). "The genetic ailment known as cystic fibrosis is an autosomal recessive condition that arises from mutations in the cystic fibrosis transmembrane conductance regulator gene, or cystic fibrosis transmembrane conductance regulator (CFTR)." (PMID 41292569, 2025). "For example, CRISPR/Cas9 repair of CFTR mutations in cystic fibrosis patient-derived intestinal organoids restored ion channel function, while retinal organoids were corrected for mutations linked to inherited blindness, demonstrating its potential for degenerative diseases." (PMID 41278202, 2025). "Similarly, dysregulation of CFTR, as observed with the rs4727853 variant, has been linked to altered macrophage activity and immune responses in conditions like cystic fibrosis, suggesting a potential role in GM, particularly in steroid-resistant cases." (PMID 39796280, 2025). "In Georgian cystic fibrosis patients, 29 CFTR mutations were identified." (PMID 40559180, 2025). "Cystic fibrosis is a life-threatening genetic disorder caused by mutations in the cystic fibrosis transmembrane conductance regulator (CFTR) gene, leading to dysfunctional chloride transport and thickened mucus secretions in multiple organ systems, particularly the lungs and pancreas." (PMID 40363673, 2025). "The aim of this review is to elucidate the complex relationships between CFTR gene mutations and gut microbiota dysbiosis in patients with cystic fibrosis, with a particular emphasis on the clinical implications of these interactions and their potential to inform novel therapeutic strategies." (PMID 41009994, 2025). "For example, severity of cystic fibrosis is affected by several genes beyond CFTR, and studies of loss of function variants in general populations revealed cases where a strong disease phenotype is expected but not observed, implying the presence of compensating variants." (PMID 38389099, 2024). "Cystic fibrosis, a genetic disorder that primarily affects the lungs and digestive system, is caused by mutations in the cystic fibrosis transmembrane conductance regulator (CFTR) gene, which leads to the production of defective CFTR proteins." (PMID 39224588, 2024). "Cystic fibrosis is the most common autosomal recessive disease in the Caucasian population, and it is caused by mutations in the CF transmembrane conductance regulator (CFTR) gene." (PMID 39685886, 2024). "Traditional genetic analysis is best suited to diagnose monogenic conditions, such as Duchenne muscular dystrophy (Duchenne MD), resulting from dystrophin mutations, or cystic fibrosis, which is caused by cystic fibrosis transmembrane conductance regulator (CFTR) mutations." (PMID 39376536, 2024). "What is more interesting is that gene mutations resulting in the mistranslation of CFTR can directly cause cystic fibrosis, suggesting a subtle connection between the fundamental mechanisms of SSS and cystic fibrosis, whether by coincidence or inevitability." (PMID 39534498, 2024). "Ivacaftor (also referred to as VX-770), developed by Vertex Pharmaceuticals, is a highly effective CFTR potentiator approved for the treatment of lung disease in Cystic Fibrosis in patients with genetic mutations associated with decreased CFTR channel function." (PMID 38982492, 2024). "Cystic fibrosis is a common severe autosomal recessive disorder caused by cystic fibrosis transmembrane conductance regulator (CFTR) gene variants, with the highest prevalence in Europe, North America, and Australia, affecting about 1 in 2000–3000 Caucasian population newborns." (PMID 39430919, 2024).